INS (insulin)
Diseases named in the same sentence as INS in open-access papers (continued):
Sharing a sentence is not in itself a finding about the gene and the disease.
Hepatic steatosis (continued). "The results showed higher plasma FGF-21 levels in obese youth, especially in those with fatty liver, independently from BMI, visceral fat, and insulin sensitivity." (PMID 33889132, 2021). "As already shown, adipose tissue IR was correlated with the severity of muscle and liver insulin sensitivity, as well as with hepatic steatosis." (PMID 35111794, 2021). "The results of the present study suggest that the selective up-regulation of protein chaperones by TMP alternative supplementation in the liver should improve insulin action and hepatic steatosis." (PMID 33807173, 2021). "Oestrogen has been shown to contribute directly to alleviating fatty liver by disrupting insulin’s effects, promoting liver fat storage, reducing oxidative damage, and inhibiting TG synthesis." (PMID 33849585, 2021). "Gut-restricted FXR agonist fexaramine (Fex) induces browning white adipose tissue, increases the metabolic rate in brown adipose tissue, alters bile acid composition, and improves hepatic steatosis and insulin sensitivity." (PMID 34745420, 2021). "Previous research found that PAE significantly decreased serum insulin and glucagon levels, improved insulin sensitivity and serum lipids profiles, and alleviated hepatic steatosis in Sprague-Dawley rats." (PMID 33638949, 2021). "IR is essentially a decrease in the sensitivity of whole-body, liver, and adipose tissue to insulin, which is involved in the development of hepatic steatosis (E. Bugianesi, 2010)." (PMID 34901163, 2021). "Oleic acid (OA) was shown to induce hepatic steatosis but with normal insulin sensitivity; this was attributable to activation of the G protein-coupled receptor 40 (GPR40)-phospholipase C (PLC)-calcium pathway by OA and upregulation of PPARδ." (PMID 34140896, 2021). "Roles of Mondo family on body weight, hepatic steatosis and insulin sensitivity according to mouse models, depending on nutritional status, genetic background and drug administration." (PMID 33868181, 2021). "Previously, we found that hepatic steatosis results in an altered hepatokine secretion profile, thereby inducing skeletal muscle insulin resistance via inter-organ crosstalk." (PMID 34707570, 2021). "Hepatic steatosis and ceramide were increased by fructose-rich diet, but reversed by returning to a control diet, while altered hepatic response to insulin persisted." (PMID 33921866, 2021). "In the present study, we observed that hAMSCs-CM was able to improve HFD-induced metabolic disorders by reducing weight gain, improving insulin sensitivity, alleviating hepatic steatosis, and enhancing energy expenditure." (PMID 34174964, 2021). "Of note, the most important finding was that adipocyte-specific deletion of JNK1 improves liver insulin sensitivity and liver steatosis." (PMID 34943809, 2021). "The findings revealed that the treatment improved insulin sensitivity, protected from hyperlipidaemia, and also prevented hepatic steatosis in the animals." (PMID 34359462, 2021). "Weight gain, lipid profile change, hepatic steatosis, as well as inflammation and insulin resistance-related gene expressions decreased." (PMID 33802777, 2021). "Metreleptin is a recombinant human leptin analogue used in lipodystrophic disorders treatment, lowering hepatic steatosis and improving insulin sensitivity, hyperglycemia, and hypertriglyceridemia." (PMID 34444990, 2021). "It has also been proposed that elevated lipocalin levels in PBC patients inhibit hepatic gluconeogenesis, resist hepatic fat accumulation, are anti-inflammatory, enhance insulin sensitivity, and reduce insulin resistance, thereby reducing hepatic steatosis." (PMID 34686147, 2021). "Betaine are nutritional antioxidants, also used in fatty liver treatment due to its anti-inflammatory, cytoprotective, antiapoptotic, and anti-steatogenic action, thus increasing insulin sensitivity." (PMID 34444990, 2021).
Hepatic steatosis (continued). "Recently, it has been investigated that various types of hepatokines such as fetuin A and B secreted by hepatocytes are increased in hepatic steatosis resulting in decreased insulin signaling, inflammation, lipolysis and insulin resistance." (PMID 34168217, 2021). "HFD+E-mice showed lower body weight (p < 0.01), amelioration of insulin-sensitivity (p = 0.021), total cholesterol (p = 0.014), low-density-lipoprotein-cholesterol (p < 0.001), alanine-aminotransferase (p = 0.038) and hepatic steatosis compared to HFD-mice." (PMID 33924725, 2021). "Regarding the intrahepatic steatosis, previous data suggest that GLP-1 agonists improve hepatic steatosis by reduction of de novo lipogenesis and improving insulin signaling pathways." (PMID 33808404, 2021). "Levels of HbA1c, fasting glucose, 2-h glucose, fasting insulin, 2-h insulin and HOMA-IR were also associated with hepatic steatosis derived from ultrasound or MRI." (PMID 34168217, 2021). "Pref-1 showed strong correlations with various metabolic conditions, including hepatic steatosis, blood pressure, and insulin sensitivity." (PMID 34229599, 2021). "These improvements involved a reduction in liver weight, hepatic steatosis, inflammation, fibrosis and partially improved insulin sensitivity." (PMID 34684533, 2021). "It is important to note that n-3 PUFAs have an anti-inflammatory effect, regulate hepatic lipid consumption, and improve insulin sensitivity, while n-6 PUFAs are considered pro-inflammatory molecules and contribute to hepatic steatosis." (PMID 34681787, 2021). "Positive metabolic actions are registered for adropin, a hepatokine that improves insulin sensitivity, hepatic steatosis and reduces adiposity." (PMID 35111794, 2021). "In the present study, the impact of supplementation with this specific combination of metabolic cofactors was evaluated for the first time, focusing on the main features of NAFLD/NASH, liver steatosis, hepatic inflammation and hepatic insulin resistance." (PMID 34684533, 2021). "Increased liver steatosis the enriched glucagon-signaling pathway, adipocytokine signaling pathway, insulin resistance in the liverdecrease in the genus Turicibacter in the gut." (PMID 33918456, 2021). "Further, dietary supplementation with Leu or Ile reduced body weight by regulating lipid metabolism-related genes and insulin sensitivity and alleviated hepatic steatosis." (PMID 34115318, 2021). "Logistical regression analysis showed that only fasting insulin was a significant predictor for hepatic steatosis." (PMID 34440963, 2021). "M-EML also alleviates high plasma glucose and insulin and insulin resistance and hepatic steatosis (area of liver steatosis)." (PMID 34441028, 2021). "In summary, these data indicate that the lack of P2Y14R in adipocytes protected mice from the development of liver steatosis and hepatic insulin resistance." (PMID 34027896, 2021). "Park found that cortisol extracts from the stems of A. senticosus reduced lipid synthesis in the liver and reduced the insulin concentration, leading to amelioration of liver steatosis." (PMID 33571255, 2021). "Among patients with T2DM and NAFLD, GLP-1RA treatment improves body composition, glycemic control, insulin sensitivity, and biomarkers of inflammation and hepatic steatosis." (PMID 33897616, 2021). "Liver-specific deletion of TSC1 (LTsc1KO), which results in insulin-independent activation of mTORC1, protected against age- and diet-induced hepatic steatosis and led to hepatocyte-intrinsic defects in SREBP1c activation and DNL." (PMID 33923817, 2021). "GLP-1 receptor (GLP-1R) agonism was found to reduce body weight and hepatic steatosis, as well as increased hepatic fatty acid oxidation and insulin sensitivity in NAFLD/NASH." (PMID 36994336, 2021).
Hepatic steatosis (continued). "In those animals, resistance to diet‐induced hepatic steatosis seems to be due at least in part to an increased feedback inhibition of insulin signaling at the level of the insulin receptor substrate 1 through S6K1‐dependent and ‐independent mechanisms." (PMID 34231324, 2021). "During the follow-up period of 5 years, the proportion of patients with insulin use increased while BMI and the proportion of patients with fatty liver, fasting glucose, and HbA1c decreased significantly." (PMID 33427937, 2021). "Our data demonstrate that AgRP neurons have a role in mediating the effects of GCs on hepatic steatosis and insulin homeostasis." (PMID 34215821, 2021). "Adiponectin is an antidiabetic adipokine, which has an insulin sensitizing effect on different metabolic tissues and can prevent the development of hepatic steatosis." (PMID 34027896, 2021). "This meta-analysis demonstrated that GLP1-RA treatment improved hepatic steatosis, liver function, lipid, glucose, inflammatory and insulin sensitivity markers, which indicates a synergistic treatment approach for patients with T2DM and NAFLD." (PMID 33897616, 2021). "It has been shown that deletion of myostatin in mice increases muscle mass and reduces adiposity, increases insulin sensitivity and glucose uptake and protects from hepatic steatosis." (PMID 35111794, 2021). "PPARγ in the liver plays a role in regulating the homeostasis of triglyceride, leading to hepatic steatosis, but alleviating triglyceride accumulation and insulin resistance in other tissues." (PMID 34443619, 2021). "Compared with HFD treatment, ML‐inulin supplementation significantly decreased weight gain, hepatic steatosis, chronic inflammation, and increased insulin sensitivity, energy expenditure and thermogenesis." (PMID 34262707, 2021). "Our promising results showed that CTD-002 reduces hepatic steatosis and improves insulin sensitivity in Sprague-Dawley rats." (PMID 34335574, 2021). "For example, cortisol extracts from the stems of A. senticosus were shown to reduce lipid synthesis in the liver and reduce the insulin concentration to ameliorate liver steatosis." (PMID 33571255, 2021). "Liver-specific Bvra−/− was found to have reduced Pparα activity and increased plasma glucose and insulin levels, with increased hepatic steatosis." (PMID 34943131, 2021). "For example, USP10 expression is decreased and upregulated in hepatic steatosis models to inhibit hepatic steatosis, insulin resistance, and inflammation." (PMID 34412625, 2021). "Recently, we showed that extracellular CTSD inhibition led to reduced hepatic steatosis and insulin sensitivity in rats." (PMID 34335574, 2021). "Activation of SREBP-1 due to high blood insulin level plays a key role in the induction of lipogenesis that leads to hepatic steatosis." (PMID 34441028, 2021). "It has been shown that patients that undergo chronic peritoneal dialysis only develop hepatic steatosis when insulin is infused to the peritoneal fluid dialysis." (PMID 33921359, 2021). "In conclusion, chronic feeding of BE to STZ/HFD-induced T2DM in rats prevents hepatic steatosis and liver damage by its hypoglycemic and insulin-sensitizing effects and its ability to upregulate antioxidants and PPARα." (PMID 34943221, 2021). "High levels of insulin can advance hepatic steatosis via impaired skeletal muscle and hepatic insulin signaling." (PMID 34943908, 2021). "It was shown in preclinical models that administration of FGF21 or its mimetics and analogs reduces body weight, blood glucose levels, improves blood lipid profiles, increases insulin sensitivity, and protects from fatty liver disease in obese animals." (PMID 34943946, 2021). "Both blood glucose and blood insulin increased significantly with the severity of fatty liver disease (P < 0.05)." (PMID 33879188, 2021).
Hepatic steatosis (continued). "An improved optogenetic device with a longer period of high-fat diet study would warrant future studies to test the effect of light-activated adipose tissue thermogenesis on systemic glucose homeostasis, insulin sensitivity, and hepatic steatosis." (PMID 32265443, 2020). "Ascorbate ameliorates hepatic steatosis and improves insulin sensitivity through inhibiting lipogenesis and SOCS3." (PMID 32158492, 2020). "In db/db mice, empagliflozin prevented hepatic steatosis, but insulin alone elevated TG in the liver." (PMID 33551821, 2020). "The deposition of lipids in the liver and insulin resistance are considered the key factors contributing to hepatic steatosis development." (PMID 32937828, 2020). "In this study, we investigated the relationship between the consumption of alcohol and the prevalence of fatty liver and resistance to insulin in Japanese men." (PMID 32283773, 2020). "Taken together, these results show an effect of DPP-4 inhibition on hepatic steatosis that is induced by the acute inhibition of IR/IGF1R signaling through an insulin signaling-independent pathway." (PMID 33105604, 2020). "In general, the liver histology is quite similar to that in ob/ob mice, and db/db mice are also obese, hyperphagic, insulin-resistant, hyperglycemic and hyperinsulinemic and develop hepatic steatosis." (PMID 33374435, 2020). "In mice, the expression of E4orf1 by transgenic approach or via viral vector reduces hepatic steatosis, improves glycemic control, and reduces the endogenous insulin response to glucose load." (PMID 32286259, 2020). "DAGs and ceramides are two bioactive lipid metabolites that are thought to link hepatic steatosis to hepatic insulin resistance." (PMID 32907986, 2020). "While AAV encoding insulin fused to albumin exacerbated liver steatosis in several mice, AAV encoding insulin fused to apolipoprotein A-I reduced liver steatosis." (PMID 33679386, 2020). "In contrast, mice with hepatocyte-specific Cd36 deletion were protected against HFD-induced liver steatosis and, even, improved whole-body insulin sensitivity." (PMID 32978374, 2020). "We next compared metabolic parameters including glucose, insulin and liver steatosis in the chimeric animals." (PMID 32452759, 2020). "An inducible model of hepatic acid ceramidase (ASAH) overexpression and ceramide deacylation has been developed previously and used to demonstrate improved insulin sensitivity and hepatic steatosis in high-fat diet-fed mice." (PMID 32398264, 2020). "Improved insulin sensitivity and reduced hepatic steatosis were observed in HFD-induced QSPHK1 mice." (PMID 33208918, 2020). "Intriguingly, heterozygous Kmt2d+/− mice exhibit metabolic alterations consisting of enhanced glucose tolerance, insulin sensitivity, and increased serum bile acid as well as resistance to over-nutrition-induced hepatic steatosis." (PMID 32668765, 2020). "Such high glycemic index foods increase hepatic steatosis, especially in insulin-resistant participants." (PMID 32605646, 2020). "HFD-reversal prompted rapid weight loss, normalization of fat pads, glucose/insulin concentrations and reduced hepatic steatosis assessed by NAS steatosis scoring." (PMID 31389294, 2020). "Adipocyte-specific depletion of SPTLC2, a critical subunit within the SPT complex, or DES1 improved insulin sensitivity, resolved hepatic steatosis, and decreased inflammation of the adipose beds." (PMID 33072120, 2020). "It was shown previously that a high-fat diet promotes hepatic steatosis and affects the β-oxidation status and balance of oxidants, which has effects on body weight, insulin signaling and other metabolic parameters." (PMID 33302947, 2020). "Hepatic steatosis is an independent predictor of cardiovascular disease, possibly by contributing to hepatic insulin resistance resulting in atherogenic dyslipidaemia." (PMID 31690988, 2020).
Hepatic steatosis (continued). "The prevalence of fatty liver and resistance to insulin was shown to be the lowest in the MD group, whereas they were observed to be the highest in the ND group." (PMID 32283773, 2020). "The improved hepatic steatosis and insulin sensitivity was due to an upregulation of hepatic HO-1 by PSO supplementation." (PMID 33327438, 2020). "FGF15/19 has been known that is able to increase metabolic rate and BAT-mediated energy expenditure concurrently with an increase in fatty acid oxidation, leading to reduced hepatic steatosis and enhanced insulin sensitivity." (PMID 32040532, 2020). "In a tissue-specific analysis of insulin sensitivity, we found that DSAT thickness associates with circulating TG levels, muscle insulin resistance, and hepatic steatosis." (PMID 31838512, 2020). "Other studies have also determined that hepatic steatosis and insulin sensitivity, and therefore the control of gluconeogenesis, are regulated through FOXO1 in an ERα-dependent manner in male mice." (PMID 33289482, 2020). "Reduction of hepatic steatosis in ω3PL-H mice is likely to be associated with reduced mesenteric WAT only indirectly, through improved insulin sensitivity and modulation of intestinal lipid transport and metabolism." (PMID 32660007, 2020). "We report here that the fusion of single-chain insulin to apolipoprotein A-I generates a novel basal insulin that is accumulated in the liver and reduces body weight and hepatic steatosis." (PMID 33679386, 2020). "We found that insulin treatment aggravated hepatic steatosis and oxidative stress in Zucker diabetic fatty (ZDF) rats." (PMID 33746742, 2020). "In adipose tissue, inhibition of lipolysis improves glucose metabolism and insulin sensitivity, whereas in liver tissue, increasing lipolysis facilitates the attenuation of hepatic steatosis." (PMID 32265720, 2020). "Studies reveal that altering sphingolipid acylation patterns impacts hepatic steatosis, adiposity, adipocyte size, adipokine secretion, macrophage infiltration, inflammation, insulin sensitivity, mitochondrial dysfunction, and ER stress." (PMID 32849276, 2020). "Our data indicated that although insulin signaling is involved in the development of hepatic steatosis, an alternative pathway that improves liver steatosis without altering insulin signals likely exists in the OSI-906-treated model." (PMID 33105604, 2020). "Further it is reported that deletion of Cd36 improved hepatic steatosis, insulin sensitivity, and reduced systemic inflammation." (PMID 31921324, 2020). "Quercetin enhanced hepatic insulin sensitivity and reduced liver fat content and ameliorated hepatic steatosis." (PMID 32785059, 2020). "The increase of energy expenditure promoted by irisin, through PPAR-α-dependent signaling, improves insulin sensitivity and reduces hepatic steatosis by upregulating FGF21." (PMID 32443765, 2020). "Even in the liver of males, estrogen action is relevant for the regulation of glucose homeostasis, insulin sensitivity, lipid metabolism, and in the prevention of hepatic steatosis." (PMID 33071979, 2020). "The mentioned factors are involved with the regulation of fatty acids metabolism, insulin sensitivity, prevention of hepatic steatosis, and interestingly they contribute to the anti-inflammatory milieu in NASH/NALFD." (PMID 33266360, 2020). "The targeted resveratrol attenuated hepatic steatosis and improved hepatic insulin sensitivity in dietary-induced obese NAFLD mice through modulation of AMPK/SIRT1/FAS/SREBP1c signaling pathway." (PMID 33327438, 2020). "In a previous study, luteolin improved insulin resistance and hepatic steatosis by suppressing hepatic lipogenesis and lipid absorption in a HFD mouse model." (PMID 33379198, 2020). "FGF21 is an important metabolic hormone that improves insulin sensitivity and decreases hepatic steatosis." (PMID 33327438, 2020). "Ablation of Degs1 in ob/ob mice also reversed hepatic steatosis and ameliorated whole-body insulin sensitivity." (PMID 32887221, 2020).